USP13 (ubiquitin specific peptidase 13)
Diseases named in the same sentence as USP13 in open-access papers (continued):
Sharing a sentence is not in itself a finding about the gene and the disease.
tumor (continued). "qRT-PCR was performed to evaluate expression of USP13 gene in 10 PCa tumor tissue samples." (PMID 36564767, 2022). "Targeting USP13 may inhibit tumor growth and provide additional benefits in cooperation with DDR inhibitors and immunotherapy." (PMID 36564767, 2022). "Considering the importance of DDR in cancer therapy, targeting USP13 may synergize with anti-tumor drugs." (PMID 36188217, 2022). "B. USP13 was highly expressed in 52 pairs of PCa tumor and adjacent normal tissue samples." (PMID 36564767, 2022). "In addition, IHC analysis and oil red O staining of tumor tissues indicated that USP13-dependent FASN expression increases lipogenesis." (PMID 35898882, 2022). "The activity, expression, and cellular localization of CK2 components could further impact USP13 phosphorylation in response to intrinsic or extrinsic cellular stresses in the tumor microenvironment." (PMID 36612196, 2022). "Further in vivo animal studies revealed TVB-2640 sensitized chemotherapy-resistant tumor cells to etoposide treatment and inhibited USP13-dependent cancer stemness and tumor growth, suggesting a crucial role of lipogenic pathway in SCLC proliferation and drug resistance." (PMID 35898882, 2022). "A. Expression of USP13 was detected in normal and tumor tissues in 15 tumor types by Gepia." (PMID 36564767, 2022). "Furthermore, tumor tissues from the USP13 knockdown group had a prominently lower USP13 and Ki-67 staining density compared to samples from the control group (P < 0.05)." (PMID 33195243, 2020). "The upregulated expression of USP13 in tumor tissues indicated that it might function as an oncogenic in HCC." (PMID 33195243, 2020). "Tumor heterogeneity leads to differential expression of USP13 in different HCC cell lines." (PMID 33195243, 2020). "Moreover, the expressions of TLR4, MyD88, and P-NF-κB p65 in subcutaneous tumor tissues from the USP13 knockdown group were prominently lower than those in the control group (P < 0.05)." (PMID 33195243, 2020). "Interestingly, the positive staining of USP13 was closely correlated with tumor size ≥ 5 cm and advanced tumor stage and conferred to significantly lower survival of HCC patients." (PMID 33195243, 2020). "Having found that USP13 is capable of blocking NF-kB induced PTEN downregulation, we further attempted to verify whether USP13 functions as a tumor suppressor in NF-kB-driven tumorigenesis of BC." (PMID 31200745, 2019). "This supported our idea that USP13 might play as a tumor suppressor by blocking PTEN downregulation." (PMID 31200745, 2019). "Hence, we concluded that USP13 acted as a tumor suppressor in BC, a downstream effector of NF-kB signaling and a crucial regulator of PTEN protein." (PMID 31200745, 2019). "Indeed, when we subcutaneously implanted TOV-21G and SW-1573 cells into nude mice, USP13 knockout dramatically retarded tumor growth in xenograft models." (PMID 29335437, 2018). "We subsequently investigated the impact of USP13-mediated MCL1 stabilization on tumor malignancy." (PMID 29335437, 2018). "However, in the context of hypoxic or oxidative stresses, USP13 loss caused a substantial decrease of cell viability and a significant increase of cell apoptosis in both TOV-21G and SW-1573 tumor models." (PMID 29335437, 2018). "USP10 and USP13 may act as a suppressor in BC by promoting autophagy in tumor cells." (PMID 40083330, 2025). "Interestingly, another two studies demonstrated that USP13 could promote tumor progression by deubiquitinating Myc, ACLY and OGDH31, 32, indicating the opposite role of USP13 in tumor progression or inhibition." (PMID 37151889, 2023). "Therefore, inhibit USP13 or RAP80 may increase the efficacy of anti-tumor drugs, and the consequent suppression of DDR should be concerned." (PMID 36188217, 2022). "Additionally, USP13 was upregulated in gastric cancer, and this upregulation may promote advanced tumor stage by stabilizing Snail, an inducer of epithelial–mesenchymal transition (EMT) and metastasis." (PMID 36188217, 2022).
tumor (continued). "The results showed that mice inoculated with USP13-deficient cells evidently formed smaller tumor masses than those inoculated with control cells, and this reduction was abrogated by reconstituted expression of shRNA-resistant WT USP13 but not the catalytically inactive USP13 (C345A) mutant." (PMID 35898882, 2022). "Hence, our data strongly indicated that USP13 promotes SCLC tumor growth." (PMID 35898882, 2022). "Furthermore, restoration of either USP13 or PTEN could partially reduce the tumor growth induced by NF-kB." (PMID 31200745, 2019). "Finally, miR‐367 silencing also significantly inhibited 3D cell invasion in tumor spheroids of both USP13‐MED and USP7‐ATRT cells, suggesting that miR‐367 silencing inhibits two key features of tumor aggressiveness, namely, stem‐like properties and invasive behavior." (PMID 31402560, 2019). "To determine whether spautin-1 as a USP13 inhibitor could sensitize tumor cells to ABT-263, we performed dose matrix experiments containing a range of drug concentrations and analyzed the effects of combining ABT-263 and spautin-1 using the Bliss independence model." (PMID 29335437, 2018). "Ubiquitin-specific protease 13 (USP13) is a deubiquitinating enzyme that stabilizes phosphatase and tensin homolog deleted on chromosome 10 (PTEN), a well-established tumor suppressor involved in PI3K/AKT signaling." (PMID 42195268, 2026). "A comparative analysis of tissue microarrays from CRC patients revealed that USP13 and MKK3 were significantly overexpressed in tumor tissues compared to adjacent normal tissues." (PMID 41307804, 2025). "Conversely, deubiquitinases USP13 and USP30 stabilize ACLY, promoting tumor progression in cancers such as ovarian and liver cancers." (PMID 40370434, 2025). "This correlation between USP13 and CD31 in tumors has significant implications for our understanding of tumor biology, particularly regarding angiogenesis." (PMID 40746889, 2025). "After observing the tumor-promoting effect of USP13 on CRC development in the mouse model, we further examined the expression of USP13, MKK3, and Ki-67 in CRC tissues from patients using immunohistochemistry (IHC)." (PMID 41307804, 2025). "Genetically deletion of USP13 or MKK3 suppressed CRC cell proliferation, migration in vitro and tumor formation in vivo, effects that were synergistically enhanced by the pharmacological inhibition of p38 signaling." (PMID 41307804, 2025). "The results showed that USP13 and MKK3 expression was significantly elevated in tumor tissues compared to adjacent normal tissues." (PMID 41307804, 2025). "For investigating the relation of USP13 expression with MVD of CRC and adjacent tissues, serial sections of tumor and adjacent tissues from 40 clinical CRC patients were subjected to IHC assay for USP13 and CD31 staining." (PMID 40746889, 2025). "USP13 stabilizes PTEN via direct binding to and de-ubiquitinating it, followed by inhibiting PI3K/AKT signaling and tumor growth in several cancer types and inhibiting the progression of other diseases, such as osteoarthritis and idiopathic pulmonary fibrosis." (PMID 36732432, 2023). "There were positive correlations among USP13, MYC, and SOX2 at the protein level in human LUSC Clinical Proteomic Tumor Analysis Consortium (CPTAC) proteomic data." (PMID 38093367, 2023). "USP13 is a DUB and plays key roles in various biological processes including tumor promotion or inhibition, inflammation, apoptosis, drug resistance and anti-viral responses by cleaving ubiquitin molecules from associated substrates." (PMID 37151889, 2023). "USP13 (F = 24.25, p = 1.00 × 10−05) and USP14 (F = 11.88, p = 1.17 × 10−03) expression were both decreased in CPh compared to non-tumor tissue." (PMID 37892185, 2023). "It is assumed that overexpression of USP13 can block AKT signaling pathway, suppressing tumor cell proliferation, invasion, and glycolysis through up-regulating PTEN protein levels." (PMID 35445009, 2022).
tumor (continued). "USP13-mediated FASN stability promoted SCLC stemness and lipogenesis, accelerating SCLC tumor growth." (PMID 36188217, 2022). "As expected, we found that USP13 knockdown markedly inhibited the proliferation, EMT, migration, and invasion of HCC cells and significantly repressed tumor growth and lung metastasis of HCC in vivo." (PMID 33195243, 2020). "Immunohistochemistry was performed to identify the protein expression of USP13, NF-kB p65 or PTEN in clinical/xenograft tumor tissues." (PMID 31200745, 2019). "Restoration of USP13 or PTEN significantly rescued the invasive cell phenotypes and xenograft tumor growth." (PMID 31200745, 2019). "We further report that genetic or pharmacological inhibition of USP13 considerably reduces MCL1 protein abundance and significantly increases tumor cell sensitivity to BH3 mimetic inhibitors targeting BCL-2 and BCL-XL." (PMID 29335437, 2018). "We perform a human deubiquitinase short interfering RNA (siRNA) library screen and identify that USP13 (ubiquitin-specific protease 13) functions as a novel MCL1 DUB to enhance its stability and promote tumor survival." (PMID 29335437, 2018). "Taken together, our results indicated that pharmacological inhibition of USP13 by spautin-1 reduced MCL1 protein abundance and increased tumor cell sensitivity to ABT-263." (PMID 29335437, 2018). "In conclusion, we identified USP13 as a novel deubiquitinase to stabilize MCL1 and modulate tumor cell sensitivity to BH3 mimetic inhibitors." (PMID 29335437, 2018). "In the immunohistochemical (IHC) analysis using a tumour tissue microarray including 118 OVCA samples and 16 adjacent normal tissues, expression of USP13 was scored according to the staining intensity and proportion of signals in each sample." (PMID 27892457, 2016). "Notably, we observed that KD of USP13 had relatively less effect on the SKOV3-derived tumours regarding tumour weight (48.7% reduction, P<0.001) and number of nodules (31.2% reduction, P=0.0036), suggesting that targeting USP13 may have therapeutic selectivity on the USP13-amplified OVCAs." (PMID 27892457, 2016). "Statistical analysis confirmed that, regardless of whether the samples were paired or unpaired, the expression levels of USP13, MKK3, and Ki-67 were consistently and significantly elevated in tumor tissues compared to adjacent normal tissues." (PMID 41307804, 2025). "USP13 downregulated VEGFA and inhibited tumor angiogenesis via the PTEN-AKT pathway." (PMID 40746889, 2025). "Based on these findings, we propose that USP13 may inhibit VEGFA expression by deubiquitinating and stabilizing PTEN, ultimately reducing tumor angiogenesis in CRC cells." (PMID 40746889, 2025). "Interestingly, USP7 and USP13 had similar mock and ZIKV-treated tumor/non-tumor cell proportions at 7 dpi." (PMID 39599878, 2024). "USP13 is preferentially expressed in glioma stem cells (GSCs), and potently promotes GSC proliferation and tumor growth by inhibiting c-Myc ubiquitination and degradation, a critical transcriptional factor for maintaining GSC self-renewal and tumorigenic potential." (PMID 36732432, 2023). "In the Swartling dataset, the expression of USP25 was downregulated in the SHH group compared to non-tumor controls (t = 14.37, p = 3.17 × 10−41), while the expression of USP13 was elevated compared to non-tumor tissues (t = 11.36, p = 1.41 × 10−27)." (PMID 37892185, 2023). "We also analyzed the methylation of the USP13 promoter in PAAD, HNSC, ccRCC and UCEC, and the results suggested that the USP13 promoter was hypermethylated in PAAD and ccRCC tumor tissues and hypomethylated in HNSC tumor tissues compared with normal tissue samples." (PMID 36564767, 2022).
tumor (continued). "In addition, clinical data showed that USP13 overexpression led to a short survival cycle and poor prognosis for OVCA patients and is closely related to tumor grade." (PMID 35445009, 2022). "Overexpression of USP13 remarkably decreased the protein levels of glucose transporter-1 (GLUT1) and hexokinase-2 (HK2) and therefore reduced glucose uptake and lactate production, which are essential energy providers for tumor cells." (PMID 36188217, 2022). "We next determined the role of USP13 in tumor growth by subcutaneously injecting H1048 cells with or without USP13 depletion, or USP13 depletion combined with WT USP13 or catalytically inactive USP13 (C345A) mutant overexpression in mice." (PMID 35898882, 2022). "Pharmacological inhibition of USP13 with spautin-1 significantly inhibits tumor growth and increases tumor cell sensitivity to BH3 mimetic inhibitors, which suggests that targeting USP13 may be a valuable strategy for cancer treatment." (PMID 35898882, 2022). "For example, overexpression of USP13 blocks the AKT signaling pathway and suppresses tumor cell proliferation, invasion, and glycolysis by upregulating PTEN, while USP13 levels are downregulated in breast, bladder, and oral squamous tumors, in correlation with PTEN levels." (PMID 36385557, 2022). "Thus, our study highlights a critical role of the USP13-FASN-lipogenesis axis in SCLC cancer stemness maintenance and tumor growth, and reveals a potential combination therapy for SCLC patients." (PMID 35898882, 2022). "Furthermore, IHC analysis indicated that USP13 positive expression was confirmed in 52 of 80 (65.0%) HCC cases, while only 34 of 80 (42.5%) non-tumor samples showed USP13 positive expression (P = 0.0043)." (PMID 33195243, 2020). "Furthermore, restoration of USP13 rescued PTEN expression, cell phenotypes and xenograft tumor growth which is altered by NF-kB activation." (PMID 31200745, 2019). "Finally, USP13 inhibition reduced MCL1 protein abundance and thereby increased tumor cell sensitivity to BH3 mimetic inhibitor ABT-263." (PMID 29335437, 2018). "Therefore, we propose that USP13 is a bona fide deubiquitinase for MCL1, a notion that is further supported by the endogenous interaction and correlative expression of USP13 and MCL1 only at protein levels in clinical tumor samples." (PMID 29335437, 2018). "Moreover, the interaction of USP13 and MCL1 occurred between endogenous proteins in A549, HEY and SW-1573 tumor cells." (PMID 29335437, 2018). "On the other hand, USP13 displays increased activity in human cancers and may represent a more titratable and episodic strategy for MCL1 inhibition to selectively kill tumor cells." (PMID 29335437, 2018). "CAOV3 cells expressing Dox-inducible control or USP13 shRNA (>80% KD) were used to establish xenograft tumour models in nonobese diabetic/severe combined immunodeficiency (NOD/SCID) mice." (PMID 27892457, 2016). "Protein levels of USP13, ACLY and OGDH were simultaneously reduced in the Dox-treated tumours." (PMID 27892457, 2016). "Similarly, USP13 105, USP29 111, USP35 113, and USP37 249 stabilize Snail to repress E-cadherin, enhancing epithelial-mesenchymal plasticity and driving GC cell migration and tumor metastasis in vitro and in vivo." (PMID 41208892, 2025). "Thus, disrupting USP13 to reduce c-Myc protein levels may impair GSC maintenance and effectively restrain GBM tumor growth." (PMID 36188217, 2022). "In addition, we explored whether pharmacological inhibition of USP13 downregulated MCL1 protein expression and synergistically kill tumor cells in combination with ABT-263." (PMID 29335437, 2018). "Besides, USP13 depletion dramatically inhibited cancer cell proliferation and suppressed tumor growth in xenograft models while reintroduction of MCL-1 partly restored cell proliferation and increased the tumor volume, reinforcing the regulation of MCL-1 by USP13." (PMID 36188217, 2022).
tumor (continued). "Moreover, IHC staining analysis in tumor tissues showed that Nanog and Oct4 expression decreased after USP13 depletion, and this decrease was rescued by reconstituted expression of WT USP13 but not catalytically inactive USP13 (C345A) mutant." (PMID 35898882, 2022). "To further study whether TVB-2640 treatment can reverse USP13-mediated tumor formation, we subcutaneously injected H1048 cells with or without USP13 depletion, or H1048 USP13-depleted cells with reconstituted expression of shRNA-resistant WT USP13 with or without TVB-2640 treatment." (PMID 35898882, 2022). "Importantly, in addition to apply genetic approaches to modulate USP13 expression, we have tested a preclinical lead compound spautin-1 and evaluated the impact of pharmacologically inhibiting USP13 activity on MCL1 protein expression and tumor cell sensitivity to ABT-263." (PMID 29335437, 2018). "Independent of the tumor dispersion pattern into the brain organoids, these data show the capability of the LN18, U343-MG, USP7 and USP13 cells to adhere and grow in this organoid model." (PMID 39599878, 2024). "USP13, on the other hand, can deubiquitinate and stabilize MCL1, which is not sensitive to MCL-2 family inhibitors, and render tumor cells highly resistant to BH3-type chemotherapy drugs." (PMID 35445009, 2022). "Although the directs targets of BAP1 have not been fully elucidated, other melanocyte-specific tumor proteins, such as MITF, have been shown to be regulated by another deubiquitinating enzyme, named ubiquitin-specific protease 13 (USP13)." (PMID 22545102, 2012). "However, they noted that the anti-tumour function of spautin-1 in PCa is independent of USP10, USP13 and autophagy." (PMID 36564767, 2022).